TAP2 (transporter 2, ATP binding cassette subfamily B member)
Description:
ABC transporter associated with antigen processing. In complex with TAP1 mediates unidirectional translocation of peptide antigens from cytosol to endoplasmic reticulum (ER) for loading onto MHC class I (MHCI) molecules. Uses the chemical energy of ATP to export peptides against the concentration gradient. During the transport cycle alternates between 'inward-facing' state with peptide binding site facing the cytosol to 'outward-facing' state with peptide binding site facing the ER lumen. Peptide antigen binding to ATP-loaded TAP1-TAP2 induces a switch to hydrolysis-competent 'outward-facing' conformation ready for peptide loading onto nascent MHCI molecules. Subsequently ATP hydrolysis resets the transporter to the 'inward facing' state for a new cycle. Typically transports intracellular peptide antigens of 8 to 13 amino acids that arise from cytosolic proteolysis via IFNG-induced immunoproteasome. Binds peptides with free N- and C-termini, the first three and the C-terminal residues being critical. Preferentially selects peptides having a highly hydrophobic residue at position 3 and hydrophobic or charged residues at the C-terminal anchor. Proline at position 2 has the most destabilizing effect. As a component of the peptide loading complex (PLC), acts as a molecular scaffold essential for peptide-MHCI assembly and antigen presentation.
Synonyms: APT2; PSF-2; RING11; ABCB3; PSF2; D6S217E; ABC18; MHC1D2
Tractability: Antibody: UniProt predicts a signal peptide or a membrane-spanning region. PROTAC: ubiquitination databases record sites on it; its protein half-life has been measured.
Gene: Protein-coding gene on chromosome 6 (32,821,833 to 32,838,784, reverse strand). Ensembl gene ENSG00000204267.
Subcellular location: Endoplasmic reticulum membrane
Subcellular location (Human Protein Atlas): Endoplasmic reticulum; Nuclear speckles
Pathways (Reactome):
Immune System: Antigen Presentation: Folding, assembly and peptide loading of class I MHC; ER-Phagosome pathway
Gene Ontology:
Molecular function: ABC-type peptide antigen transporter activity; ATP binding; MHC class Ib protein binding; peptide antigen binding; peptide transmembrane transporter activity; protein binding; TAP1 binding; ABC-type peptide transporter activity; tapasin binding; ABC-type transporter activity; ATP hydrolysis activity; MHC protein binding
Biological process: antigen processing and presentation of endogenous peptide antigen via MHC class I; antigen processing and presentation of endogenous peptide antigen via MHC class Ib via ER pathway, TAP-dependent; cytosol to endoplasmic reticulum transport; peptide antigen transport; peptide transport; adaptive immune response; defense response; transmembrane transport
Cellular component: endoplasmic reticulum; endoplasmic reticulum membrane; membrane; MHC class I peptide loading complex; TAP complex; endoplasmic reticulum-Golgi intermediate compartment membrane; phagocytic vesicle membrane
Genetic constraint (gnomAD): Loss-of-function variants: 50 observed, 75.14 expected, observed/expected ratio (o/e) 0.67, 90% interval 0.53 to 0.84. The synonymous counts are far from expectation, so gnomAD's model fits this gene poorly and the ratio says little. Missense variants: 739 observed, 878.47 expected, observed/expected ratio (o/e) 0.84, 90% interval 0.79 to 0.89. Synonymous variants: 306 observed, 376.63 expected, observed/expected ratio (o/e) 0.81, 90% interval 0.74 to 0.89.
Gene-disease validity (ClinGen):
ClinGen rates the evidence that TAP2 causes each of these diseases.
MHC class I deficiency (autosomal recessive): Definitive.
Homologues: Orthologues: chimpanzee TAP2 (99% identical), macaque MAMU-DOB (93% identical), pig TAP2 (81% identical), rabbit TAP2 (80% identical), dog TAP2 (78% identical), mouse Tap2 (77% identical), rat Tap2 (76% identical), guinea pig TAP2 (74% identical), Caenorhabditis elegans haf-7 (29% identical), Caenorhabditis elegans haf-8 (28% identical), Caenorhabditis elegans pgp-1 (27% identical), Caenorhabditis elegans pgp-14 (26% identical), and 6 more. Paralogues in human: ABCB9 (41% identical), TAP1 (38% identical), ABCB8 (32% identical), ABCB10 (30% identical), ABCB1 (29% identical), ABCB5 (28% identical), ABCB4 (28% identical), ABCB11 (27% identical), ABCB6 (25% identical), ABCB7 (23% identical).
Diseases named in the same sentence as TAP2 in open-access papers:
TAP2 is named in the same sentence as 127 diseases in open-access papers, as found by Europe PMC text mining. Sharing a sentence is not in itself a finding about the gene and the disease. The quoted sentences say what the papers report.
melanoma (20 papers, 2010 to 2025). A malignant, usually aggressive tumor composed of atypical, neoplastic melanocytes. "The therapeutic value of ACB1801-dependent increase of TAP1, TAP2, Tapasin and Lmp2 is underscored by clinical data showing that high expression levels of these proteins was observed in melanoma patients that respond to anti-PD-1 and associated with an improved survival of melanoma patients." (PMID 36458012, 2022). "We assessed the impact of ACB1801 on the expression of antigen presentation genes (TAP1, TAP2, Tapasin, b2m, Lmp2, Lmp10, PA28α and PA26β) in murine B16-F10 melanoma." (PMID 36458012, 2022). "B16 melanoma cells are poorly immunogenic due to downregulation of transporters associated with antigen processing (TAP-1 and TAP-2), resulting in reduced MHC class I expression and a diminished ability to present antigens to CD8+ T cells." (PMID 23768240, 2013). "In previous studies, gene promoter hypermethylation was associated with downregulation of tapasin, TAP1, TAP2, and LMP7 protein expression in esophageal squamous cell carcinoma, colon cancer, renal cancer, and melanoma." (PMID 23024775, 2012). "Collectively, these results show that GGTase I inhibition enhances hIFN-γ-induced TAP1 and TAP2 expression in this human melanoma cell line." (PMID 20140259, 2010). "Also TAP2 was upregulated in human melanoma cells after IFNα therapy." (PMID 26735690, 2016). "Similar to primary melanoma cells, loss of IRF2 dropped the surface expression of MHC I and significantly reduced transcripts of TAP2, ERAP1, and PSME1 detected in B16F0 mouse melanoma cells." (PMID 39281881, 2024). "Collectively, these data highlight the therapeutic value of increasing the expression levels of TAP1, TAP2, TAPBP and PSMB9 in melanoma." (PMID 36458012, 2022). "At the end of 3-week mavorixafor monotherapy, expression scores for a panel of antigen processing and presentation genes measured in melanoma biopsies, which included B2M, TAP1/TAP2, and multiple HLA complex genes, trended toward an increase." (PMID 36923305, 2022). "To introduce fluorescent TAP-GFP into human melanoma MJS cells, we first generated, by using CRISPR/Cas9-based technology, TAP1 or TAP2 knock-outs (KO)." (PMID 31817841, 2019). "In the current study we used the LB1319-MEL human melanoma model to investigate the effects of 4 days of in vitro treatment with hIFN-γ (50 IU/mL) and/or GGTI-298 (10 μM) on the expression of TAP1, TAP2, tapasin, PA28, LMP2, LMP7, and LMP10 proteins." (PMID 20140259, 2010). "As previously observed in the murine melanoma model, the GGTase I inhibition enhances IFN-γ-induced MHC class I expression through a mechanism involving TAP1 and TAP2 over-expression." (PMID 20140259, 2010). "Using melanoma B16 cells, the authors demonstrate that the HDACi, TSA increases the expression of several components of the antigen processing machinery, including TAP-1, TAP-2, LMP-2, and Tapasin." (PMID 32500025, 2020). "Methylation of the tapasin and/or TAP2 promoter has been reported in melanoma and RCC cell lines and treatment with DNA demethylation agent 5-aza-2′-deoxycytidine (5-AC) results, not only in the enhancement and/or reconstitution of tapasin and TAP2, but also in TAP1 transcription and translation." (PMID 24212778, 2011). "We showed that melanoma patients who were responsive to anti-PD-1 expressed significantly higher levels of TAP1, TAPASIN, LMP2, but not TAP2, compared to those who were not responsive to this therapy." (PMID 36458012, 2022).
cervical carcinoma (11 papers, 2006 to 2023). A carcinoma arising from either the exocervical squamous epithelium or the endocervical glandular epithelium. "A study of 1,306 Swedish women with cervical cancer showed a strong linkage disequilibrium between the TAP2 p.Thr665Ala and DQB1 alleles." (PMID 36619767, 2022). "Regarding the p.Thr665Ala SNP of the TAP2 gene, the women’s ancestry also influenced cancer susceptibility, especially cervical cancer." (PMID 36619767, 2022). "Single-nucleotide polymorphisms (SNPs) in TAP1 and TAP2 affected their expression and were associated with cervical cancer in the Chinese Han population." (PMID 35837087, 2022). "In this sense, SNPs in TAP2 have been previously associated with a higher risk for ankylosing spondylitis and cervical carcinoma associated with HPV." (PMID 33138079, 2020). "As shown, in the Javanese population, four ERAP1 SNPs and the TAP2-651 SNP were significantly associated with cervical carcinoma occurrence, whereas in the Balinese population, only the TAP2-651 locus showed this association." (PMID 25796583, 2015). "Specifically, the combination of a minor allele at ERAP1-575 with major alleles at both TAP2 loci was associated with an increased risk of cervical cancer; the PAF for this haplotype was 3.9 %." (PMID 25796583, 2015). "In the Balinese population, only the TAP2-651 locus was significantly associated with cervical carcinoma risk, with the minor allele increasing this risk (P < 0.001)." (PMID 25796583, 2015). "Additionally, our findings strongly suggest that LMP2 and TAP2’s effects on cell growth, proliferation, and tumor growth in cervical cancer are closely associated with the modulation of Wnt1 expression." (PMID 37986152, 2023). "Few association studies on TAP2 haplotypes and cervical cancer are available." (PMID 36619767, 2022). "This may explain the controversies in the association of the TAP2 p.Thr665Ala allele with the risk of cervical cancer in different populations." (PMID 36619767, 2022). "Also, the T allele of the SNP TAP2 p.Arg651Cys was associated with an increased risk of cervical cancer in women from Bali, a region of Indonesia, while in Dutch women with HPV+, the risk was attributed to the C allele." (PMID 36619767, 2022). "Nevertheless, the viral modulation of TAP2 expression, possibly mediated by p.Val379Ile SNP allele A, may contribute to cervical cancer progression from precursor lesions." (PMID 36619767, 2022). "Specifically, in the Javanese population, a combination of the ERAP1-575 locus on chromosome 5 and the TAP2-379 and TAP2-651 markers on chromosome 6 was significantly associated with cervical carcinoma risk, whereas in the Balinese population, only the TAP2-651 locus exhibited this association." (PMID 25796583, 2015). "Taken together, our study revealed that LMP2 and TAP2 suppress the oncogenesis and metastasis of cervical cancer cells by Wnt/β-catenin pathway and altering EMT." (PMID 37986152, 2023). "The effect of LMP2 and TAP2 on the migration ability of cervical cancer cells was detected by cell scratch test." (PMID 37986152, 2023). "In this study, the mechanism of LMP2 and TAP2 impairing the oncogenesis and metastasis of cervical cancer was investigated in vitro and in vivo, which lays the foundation for the research of cervical cancer gene vaccine and dual gene nucleic acid vaccine." (PMID 37986152, 2023). "The results revealed a significant upregulation of LMP2 and TAP2 mRNA levels in cervical carcinoma tissue compared to normal tissue." (PMID 37986152, 2023). "Here we aimed to explore the effect of LMP2 and TAP2 on the oncogenesis and metastasis of cervical cancer cells." (PMID 37986152, 2023). "Our findings suggested that LMP2 and TAP2 possibly modulate the Wnt/β-catenin pathway to impair the proliferation of cervical cancer cells." (PMID 37986152, 2023).
cervical carcinoma (continued). "They identified a specific combination of four SNPs in genes encoding components of the APM (ERAP1-127, ERAP1-730, TAP2-651, and LMP7-145), which were associated with an increased cervical carcinoma risk." (PMID 32183384, 2020). "We have demonstrated that various single nucleotide polymorphisms (SNPs) in the LMP7, TAP2 and ERAP1 genes were significantly associated with risk of developing cervical carcinoma in the Dutch population." (PMID 25796583, 2015). "These experiments suggested that LMP2 and TAP2 could inhibit the migration of cervical cancer cells." (PMID 37986152, 2023). "LMP2 and TAP2 may inhibit the oncogenesis and metastasis of cervical cancer cells by inhibiting the process of EMT and the Wnt/β-catenin signaling pathway, which may provide important insight into prospective targets for the treatment of cervical cancer." (PMID 37986152, 2023). "Nevertheless, the specific role and underlying mechanism of LMP2 and TAP2 in the oncogenesis and metastasis of cervical cancer have not been elucidated." (PMID 37986152, 2023). "In conclusion, LMP2 and TAP2 may regulate the migration of cervical cancer cells by participating in the regulation of EMT." (PMID 37986152, 2023). "The expressions of LMP2 and TAP2 in cervical cancer and normal tissues were determined by qPCR." (PMID 37986152, 2023). "In the present study, we reported that LMP2 and TAP2 levels were overexpressed in cervical cancer." (PMID 37986152, 2023). "In addition, Wnt1 overexpression partially rescued the observed consequences of ectopic expression of LMP2 and TAP2 in cervical cancer cells." (PMID 37986152, 2023). "Consequently, these findings indicate that the primary mechanisms through which LMP2 and TAP2 exert their biological effects in cervical cancer predominantly involve the regulation of Wnt1." (PMID 37986152, 2023). "Another example is the lack of association between the SNPs TAP2, p.Val379Ile, p.Ala565Thr, and p.Arg651Cys, with histological and cytological alterations and cervical cancer reported in Chinese and Swedish women when compared to the control group." (PMID 36619767, 2022). "In addition, they found that up to 12% of all cervical carcinomas correlated with a particular haplotype combination that include the minor allele at the ERAP1-127 and ERAP1-730 loci, and the major allele at the TAP2-651 and LMP7-145 loci." (PMID 32183384, 2020). "In particular, while in Javanese a strong association between cervical carcinoma risk and ERAP1-575 locus on chromosome 5 and the TAP2-379 and TAP2-651 SNPs on chromosome 6 could be established, only the TAP2-651 locus correlated with carcinoma risk in Balineses." (PMID 32183384, 2020). "Allele distribution patterns in Bali and Java differed in relation to cervical carcinoma risk, with four ERAP1 SNPs and one TAP2 SNP in the Javanese population showing significant association with cervical carcinoma risk, while in the Balinese population, only one TAP2 SNP showed this association." (PMID 25796583, 2015). "The results showed that the wound width of Hela cells in the control group was significantly lower (P < 0.01) than that of cervical cancer cells after LMP2 and TAP2 transfection." (PMID 37986152, 2023). "In the present study, we found that the proliferation and migration ability of cervical cancer were significantly reduced in the LMP2 and TAP2 group compared with the control group, especially in LMP2 and TAP2 co-transfection group." (PMID 37986152, 2023). "Gelatin zymography and western blotting assays were used to detect the effect of LMP2 and TAP2 on the EMT and Wnt/β-catenin pathway in cervical cancer cells." (PMID 37986152, 2023). "Since LMP2 and TAP2 impair tumor growth and proliferation in vitro, we subsequently detected the effects of LMP2 and TAP2 on the oncogenesis of cervical cancer cells in vivo." (PMID 37986152, 2023).
cervical carcinoma (continued). "Eleven non-synonymous, coding SNPs in the TAP1, TAP2, LMP2, LMP7 and ERAP1 genes were genotyped in cervical carcinoma patients and healthy controls from two distinct Indonesian populations (Balinese and Javanese)." (PMID 25796583, 2015). "By bisulfite sequencing approach, we identified target CpG islands methylated at the gene promoter region of TAP1, TAP2, LMP7, tapasin and ERp57 in cervical carcinoma cells." (PMID 23024775, 2012). "To explore whether the presence of Wnt1 is indeed necessary for the observed effects resulting from the overexpression of LMP2 and TAP2 in cervical cancer cells, we introduced exogenous expression of Wnt1 into LMP2 and/or TAP2 overexpressed cells." (PMID 37986152, 2023).
autoimmune disease (9 papers, 2008 to 2025). A disorder resulting from loss of function or tissue destruction of an organ or multiple organs, arising from humoral or cellular immune responses of the individual to their own tissue constituents. "TAP2, a transporter associated with antigen processing, plays an important role in immune responses and autoimmune diseases." (PMID 40149556, 2025). "TAP1 and TAP2 are antigen presenting transporters and alterations in these genes associate with autoimmune diseases, susceptibility to infections, or malignancies." (PMID 33334016, 2020). "In SS-KCS mouse models, TAP2 expression exhibited quantitative and temporal variations, indicating its important role in the progression of autoimmune diseases." (PMID 40149556, 2025). "ERAP2 is reported to be associated with several other autoimmune diseases and is, as the TAP1 and TAP2 proteins, crucial for proper folding and assembly of the MHC-I heavy chain." (PMID 40883722, 2025). "The two hub mRNAs, CR1 and TAP2, play important roles in the development of Sjögren’s syndrome and other autoimmune diseases while also contributing to COVID-19 progression." (PMID 40149556, 2025). "The top three ranked genes, HLA-G, TAP2 and HLA-DRB1, are implicated in autoimmune diseases, while TAP2 is associated with SNPs characteristic for MG." (PMID 18851734, 2008). "Additional work will be required to identify novel and more specific compounds able to selectively modulate TAP2 and potentially exert controlled immunomodulatory effects for patients with cancer or autoimmune diseases (e.g. compounds that could selectively reduce TAP2 expression)." (PMID 40091029, 2025). "TAP2 is involved in defective major histocompatibility complex (MHC) class I expression and antigen presentation in autoimmune diseases, such as celiac disease and type 1 diabetes." (PMID 34567510, 2021). "In PhenoScanner49, TAP2, DCLRE1B, and SKIV2L have been previously mapped in GWAS to autoimmune disorders such as rheumatoid arthritis (RA)." (PMID 32358504, 2020).